TM4SF4 (transmembrane 4 L six family member 4)
Description:
Regulates the adhesive and proliferative status of intestinal epithelial cells. Can mediate density-dependent cell proliferation.
Synonyms: IL-TMP; ILTMP
Tractability: Antibody: UniProt predicts a signal peptide or a membrane-spanning region; the Human Protein Atlas places it where antibodies can reach. PROTAC: its protein half-life has been measured.
Gene: Protein-coding gene on chromosome 3 (149,474,697 to 149,503,394, forward strand). Ensembl gene ENSG00000169903.
Subcellular location: Membrane
Subcellular location (Human Protein Atlas): Plasma membrane; Cytosol
Gene Ontology:
Molecular function: protein binding
Cellular component: membrane
Genetic constraint (gnomAD): Loss-of-function variants: 22 observed, 20.3 expected, observed/expected ratio (o/e) 1.08, 90% interval 0.77 to 1.54. The upper end of that interval is the gene's LOEUF score, 1.54, which puts it in group 6 of 6, group 1 being the genes least tolerant of losing a copy. Missense variants: 204 observed, 222.55 expected, observed/expected ratio (o/e) 0.92, 90% interval 0.82 to 1.03. Synonymous variants: 95 observed, 83.97 expected, observed/expected ratio (o/e) 1.13, 90% interval 0.96 to 1.34.
Homologues: Orthologues: chimpanzee TM4SF4 (99% identical), macaque TM4SF4 (94% identical), dog TM4SF4 (90% identical), mouse Tm4sf4 (88% identical), rat Tm4sf4 (88% identical), pig TM4SF4 (85% identical), guinea pig TM4SF4 (81% identical), rabbit TM4SF4 (79% identical), tropical clawed frog tm4sf4 (68% identical), zebrafish tm4sf4 (61% identical). Paralogues in human: TM4SF1 (49% identical), TM4SF5 (40% identical), TM4SF18 (37% identical), TM4SF19 (29% identical), TM4SF20 (29% identical).
Diseases named in the same sentence as TM4SF4 in open-access papers:
TM4SF4 is named in the same sentence as 18 diseases in open-access papers, as found by Europe PMC text mining. Sharing a sentence is not in itself a finding about the gene and the disease. The quoted sentences say what the papers report.
lung carcinoma (7 papers, 2014 to 2026). "In this study, we demonstrated that TM4SF4 is critical for EMT-associated cancer stemness properties in lung cancer cells." (PMID 29254164, 2017). "In vitro colony formation assays demonstrated that anti-TM4SF4 mAb inhibited the proliferation of A549 lung cancer cells." (PMID 41356204, 2026). "Among the novel anti-TM4SF4 monoclonal antibodies developed, 2B7—a murine IgG1 antibody with a κ light chain—demonstrated robust antitumor effects in both in vitro and in vivo lung cancer models." (PMID 41356204, 2026). "In this study, we successfully generated monoclonal antibodies against TM4SF4—a transmembrane protein overexpressed in lung cancer cells—through immunization of mice with a short antigenic peptide derived from its LEL domain." (PMID 41356204, 2026). "In lung cancer, TM4SF4 expression is upregulated where it promotes tumor growth, migration, and invasion through activation of PI3K/AKT and JAK2/STAT3 pathways, as well as preserving cancer stem cell features." (PMID 39999090, 2025). "A study in South Korea demonstrates that TM4SF4 overexpression in lung cancer cells leads to radioresistance via IGF1-induced IGF1R activation." (PMID 36875059, 2023). "Based on these results, we discuss the use of anti-TM4SF4 antibody against TM4SF4-overexpressing and radiation-resistant lung cancer therapy." (PMID 25344917, 2014). "In these lung cancer cells, TM4SF4 overexpression increased the expression of IGF1, a ligand that activates IGF1R, which appears to be a key event in activation of the IGF1R pathway." (PMID 25344917, 2014). "IL1beta expression, which is known to facilitate metastasis of lung cancer, is also altered depending on the expression of TM4SF4." (PMID 25344917, 2014). "More importantly, we confirmed that repetitive radiation on A549 lung cancer cells increased the expression of TM4SF4." (PMID 25344917, 2014). "Immunohistochemical staining of human lung cancer tissue also confirmed that TM4SF4 is overexpressed in lung adenocarcinoma and that it can be used as an indicator of lung adenocarcinoma." (PMID 25344917, 2014). "Most of lung cancer cells examined expressed low levels of TM4SF4; however, A549 and Calu-3 cells showed exceptionally high levels of TM4SF4 expression." (PMID 25344917, 2014). "Treatment of TM4SF4-overexpressing lung carcinoma cells with anti-TM4SF4 antibody suppressed cell growth, which was mediated by suppression of IGF1 expression." (PMID 25344917, 2014). "Collectively, TM4SF4-derived signaling pathways including GSK3β/β-catenin and JAK2(or FAK)/STAT3 appear to be focused on the secretion level of OPN and thus strengthen EMT-associated CSC-like properties in lung cancer cells." (PMID 29254164, 2017). "In addition, we demonstrated the potential of combination therapy of targeting TM4SF4 and radiation against lung cancer, although at present this has been confirmed in in vitro cell-based assay." (PMID 25344917, 2014). "Further studies on the function of TM4SF4 in lung cancer cells can be started based on the interaction of TM4SF4 with other molecules, such as integrins, growth factor receptors, and cytoplasmic components, which might reveal the mechanism of IGF1 induction." (PMID 25344917, 2014). "In this study, we showed that TM4SF4 can be a therapeutic target in lung cancer." (PMID 25344917, 2014). "In addition, IL1beta expression, which is known to facilitate metastasis of lung cancer, was also altered depending on the level of TM4SF4." (PMID 25344917, 2014). "The methylation percentage of the TM4SF4 gene was also analyzed in other lung cancer cells." (PMID 25344917, 2014). "Our results suggest that TM4SF4 overexpression in lung carcinoma cells results in resistance to radiotherapy via IGF1-induced IGF1R activation and blocking the activity of TM4SF4 using specific antibody can be a promising therapeutics against TM4SF4-overexpressing lung adenocarcinoma." (PMID 25344917, 2014).
lung carcinoma (continued). "Collectively, we show that TM4SF4 in lung cancer cells mediates the activation of a positive feedback autocrine loop between OPN and STAT3 pathways, resulting in cancer stemness and radiation resistance, and suggest targeting TM4SF4 or OPN may be useful as a cancer treatment." (PMID 29254164, 2017). "In addition, anti-TM4SF4 antibody treatment enhanced radiation sensitivity of lung cancer cells." (PMID 25344917, 2014). "Our studies revealed that TM4SF4 upregulation enhanced OPN and IGF1 secretion in lung cancer cells 28, suggesting its role in modulating ICL expression." (PMID 41356204, 2026). "Overexpression of TM4SF4 in the invasive A549 NSCLC adenocarcinoma cell line, and its effects on the cellular characteristics of lung carcinoma cells, revealed that TM4SF4 is critical for tumorigenesis and radiation resistance in A549 NSCLC cells." (PMID 25344917, 2014). "We analyzed TM4SF4 levels in A549 NSCLC cells and identified TM4SF4 as an inducer of lung cancer cell tumorigenicity." (PMID 25344917, 2014). "Overexpression of TM4SF4 in lung cancer cells increased phosphorylation of IGF1R and activated signaling components of the PI3K pathway, the most important signaling pathway in lung cancer cells, including PI3K, AKT, and NK-kappaB." (PMID 25344917, 2014). "Therefore, TM4SF4 functions in cancer, especially in lung cancer, have not been studied, although other members of the tetraspanin L6 family, such as TM4SF1 and TM4SF5, have been investigated as inducers of tumorigenesis." (PMID 25344917, 2014).
hepatocellular carcinoma (6 papers, 2014 to 2026). A malignant tumor that arises from hepatocytes. "Beyond NSCLC, 2B7 inhibited the growth of other TM4SF4-expressing cancer cell lines, including Huh7 (hepatocellular carcinoma) and MIA PaCa-2 (pancreatic cancer)." (PMID 41356204, 2026). "Overexpression of TM4SF4 is shown in hepatocellular carcinoma and colorectal cancer and targeting TM4SF4 with siRNA attenuates the cell growth of hepatocellular carcinoma which implies TM4SF4 is a potential anti-cancer target." (PMID 29254164, 2017). "Only recently, it was reported that TM4SF4/IL-TMP mRNA and protein levels were upregulated in 80% of hepatocellular carcinoma tissues." (PMID 25344917, 2014). "It is reported that TM4SF4 and TM4SF5 could promote hepatocellular carcinoma (HCC) cell growth and metastasis both in vivo and in vitro." (PMID 33015133, 2020). "Additionally, Hz2B7-1.2 induced robust ADCC in MIA PaCa-2 (pancreatic cancer) and Huh7 (hepatocellular carcinoma), but not in THLE-2 (normal liver cells), confirming its specificity for TM4SF4-expressing cancer cells." (PMID 41356204, 2026).
pancreatic cancer (3 papers, 2022 to 2026). "TM4SF4 is also overexpressed in pancreatic cancers as a hub gene and upregulated in chemoresistant ovarian cancer cells." (PMID 39999090, 2025). "Although ENST00000465758.1 (one of TM4SF4 transcripts) is specifically expressed in liver cancer over normal liver tissue and any other tissue, it is also detected transcriptionally active in other cancer types, such as cholangiocarcinoma and pancreas cancer." (PMID 35473935, 2022). "Given the demonstrated effectiveness of 2B7 in hepatocellular and pancreatic cancer models, anti-TM4SF4 monoclonal antibody therapy may be broadly applicable to other TM4SF4-overexpressing tumors, supporting the development of universal CSC-targeted cancer therapies." (PMID 41356204, 2026).
liver cancer (2 papers, 2017 to 2022). An epithelial or non-epithelial malignant neoplasm that arises from the liver. "TM4SF4 is upregulated in injured liver in CCl4-treated mice, overexpressed in liver cancer tissues, and is correlated with directional migration, similar to TM4SF5." (PMID 28129652, 2017). "Meanwhile, TM4SF4 is expressed in non-dividing hepatocytes and upregulated during liver injury possibly for cellular differentiation and regeneration, although it is highly enhanced in liver cancer." (PMID 28129652, 2017).
lung adenocarcinoma (2 papers, 2014 to 2023). A carcinoma that arises from the lung and is characterized by the presence of malignant glandular epithelial cells. "The tumorigenic activity of TM4SF4 in lung adenocarcinoma was confirmed by immunohistochemical staining of the xenograft model in athymic BALB/c nude mice." (PMID 36678607, 2023). "Tumorigenic activity of TM4SF4 in lung adenocarcinoma cells was also demonstrated by xenograft assay; however, this activity was almost completely suppressed by treatment with anti-TM4SF4 antibody." (PMID 25344917, 2014). "In this study, we demonstrated that TM4SF4 is overexpressed in lung adenocarcinoma cells as a result of hypomethylation in the promoter region of the TM4SF4 gene, and it enhances activation of the IGF1R pathway and, consequently, enhances tumorigenicity." (PMID 25344917, 2014). "Here, we show that TM4SF4 is highly expressed in radiation-resistant lung adenocarcinoma cells, such as A549 and Calu-3 cells, and its expression activates cell growth, migration, and invasion via IGF1R activation." (PMID 25344917, 2014). "The therapeutic efficacy of anti-TM4SF4 antibody was evaluated in mouse xenograft models of TM4SF4-overexpressing human lung adenocarcinomas." (PMID 25344917, 2014). "Here, we show that TM4SF4 was highly expressed in radiation-resistant lung adenocarcinoma cells, such as A549 and Calu-3 cells, and its expression activated cell growth, migration, and invasion." (PMID 25344917, 2014). "Furthermore, tissue microarray analysis revealed that five of the 119 lung adenocarcinoma cases scored high TM4SF4 expression." (PMID 36678607, 2023). "Overall, these results suggest that TM4SF4 is a key protein conferring radiation resistance in lung adenocarcinoma and a combination therapy employing radiation and targeting TM4SF4 might be effective therapy against radiation-resistant lung adenocarcinoma." (PMID 25344917, 2014).
fibrolamellar carcinoma (1 paper, 2024). "TM4SF4 was markedly associated with race and sex and histological type, which suggested that Caucasian women and patients with fibrolamellar carcinoma displayed markedly higher TM4SF4 expression." (PMID 38206300, 2024).
rectum adenocarcinoma (1 paper, 2024). An adenocarcinoma arising from the rectum. "TM4SF4 was up-regulated in CHOL, COAD, HNSC, PRAD, THCA and markedly lower in BRCA, KICH, KIRC, LUSC, and Rectum adenocarcinoma (READ)." (PMID 38206300, 2024).
cancer (15 papers, 2014 to 2026). A tumor composed of atypical neoplastic, often pleomorphic cells that invade other tissues. "Moreover, neutralizing antibody treatment to inhibit TM4SF4 action significantly weakened the EMT-associated CSC-like properties of cancer cells with the reduction of the cellular TM4SF4 level." (PMID 29254164, 2017). "In particular, target-specific antibodies against molecules such as TM4SF4, which is highly expressed in cancer stem cells, are expected to make significant contributions to antitumor strategies." (PMID 41356204, 2026). "Overall, these results highlight the dual role of 2B7 in inhibiting TM4SF4-mediated cancer stemness and limiting immune evasion by suppressing ICL expression." (PMID 41356204, 2026). "In this study, we developed a murine monoclonal antibody targeting human TM4SF4 (anti-hTM4SF4 mAb), designated 2B7, which exhibited potent anti-cancer effects in NSCLC both in vitro and in vivo." (PMID 41356204, 2026). "We aimed to develop mAbs that bind to the extracellular region of TM4SF4 to inhibit its function and suppress cancer stemness in NSCLC." (PMID 41356204, 2026). "TM4SF4 has also been implicated in EMT by activating receptor tyrosine kinase (RTK) and integrin-mediated signaling pathways that are critical for EMT, cancer stemness, and angiogenesis 28,51,52." (PMID 41356204, 2026). "Despite the generally low FcγR affinity of murine IgG1 69, 2B7 exhibited potent antitumor efficacy, likely through direct blockade of TM4SF4 signaling, a crucial regulator of cancer stemness." (PMID 41356204, 2026). "To elucidate how 2B7 inhibits the cancer cell proliferation, self-renewal, and metastasis, we examined its effects on TM4SF4-related signaling pathways." (PMID 41356204, 2026). "Comparatively, only several studies have reported the regulatory roles of TM4SF4 in cancers, particularly involved in the cancer prognosis of CRC, LC, and liver cancer." (PMID 36678607, 2023). "Compared to TM4SF1, relatively fewer studies have investigated the regulatory roles of TM4SF4 in cancer." (PMID 36678607, 2023). "The sphere-forming assay, which evaluates the self-renewal capacity of cancer cells, also showed that TM4SF4 regulates the CSC-like characteristics of A549 adenocarcinoma cells." (PMID 29254164, 2017). "The candidate genes including BGN, MMP1, LGALS1, SERPINB5, and TM4SF4 probably correlated with cancer development and the EMT program mediated by the integrated pathway of TGFβ/Snail with TNFα/NFκB." (PMID 28687755, 2017). "Collectively, our findings indicate that TM4SF4-triggered OPN expression is involved in the persistent reinforcement of EMT or cancer stemness by creating a positive feedback autocrine loop with JAK2/STAT3 or FAK/STAT3 pathways." (PMID 29254164, 2017). "TM4SF4-triggered OPN expression forms the core for the persistent reinforcement of EMT or cancer stemness by creating a positive feedback autocrine loop with JAK2/STAT3 or FAK/STAT3 pathways." (PMID 29254164, 2017). "TM4SF4 knockdown weakened sphere forming and suppressed the expression of cancer stem cell markers such as ALDH1A1, ALDH1A3, Oct3/4, Sox2." (PMID 29254164, 2017). "Additionally, as an IgG1 isotype, Hz2B7-1.2 effectively mediates antibody-dependent cellular cytotoxicity (ADCC) against TM4SF4-expressing cancer cells, resulting in tumor clearance." (PMID 41356204, 2026). "However, the findings have shown that TM4SF4 plays an important regulatory role in cancer phenotypes and progression, making it a potential therapeutic molecular target for different cancer types." (PMID 36678607, 2023). "Fractionated γ-radiation (2 Gy × 3 times or 2 Gy × 9 times), which enhances EMT and cancer stemness, also significantly up-regulated the cellular TM4SF4 and OPN, indicating that these proteins may be involved in the reinforcement of γ-radiation-induced stemness in cancer cells." (PMID 29254164, 2017). "However, little is known about functions of TM4SF4 in cancer cells." (PMID 25344917, 2014).
cancer (continued). "Expression Atlas revealed that TM4SF1, TM4SF4, TM4SF18, and TM4SF19 were expressed in various cancer cell lines." (PMID 38206300, 2024). "As compared to others, this review aimed to present a focused insight and update on the biological roles of TM4SF1, TM4SF4, and TM4SF5 in the progression, metastasis, and chemoresistance of various cancers." (PMID 36678607, 2023). "Accumulating evidence has demonstrated, among six TM4SF members, the regulatory roles of transmembrane 4 L6 domain family members, particularly TM4SF1, TM4SF4, and TM4SF5, in cancer angiogenesis, progression, and chemoresistance." (PMID 36678607, 2023). "Next, we questioned how TM4SF4 activates the JAK2/STAT3 pathway or SRC/FAK/STAT3 pathway, which also reinforces EMT or CSC-like properties of cancer cells." (PMID 29254164, 2017). "Our Previous studies showed that TM4SF4 confers γ-radiation resistance through activation of the IGF1Rβ/PI3K/AKT/NFκB pathway, which is an important signaling pathway in maintaining cancer stemness." (PMID 29254164, 2017). "Collectively, these findings demonstrate that the 2B7 antibody, which showed effective antitumor efficacy in NSCLC xenograft models, inhibited TM4SF4-mediated cancer stemness and EMT and provided evidence of its therapeutic potential in extrapulmonary cancer types." (PMID 41356204, 2026). "Notably, studies utilizing outlier analysis have identified TM4SF4 and LRRK2 as key oncogenic drivers, demonstrating that transcriptomic profiling can aid in discovering novel targets for personalized cancer therapy." (PMID 40872585, 2025). "Hence, TM4SF1, TM4SF4, and TM4SF5 are promising therapeutic targets for different cancer types preclinically and deserve further investigation." (PMID 36678607, 2023). "Although direct interactors of TM4SF4 have not been identified yet, TM4SF4-mediated activation of cancer stemness or EMT properties is evident." (PMID 29254164, 2017). "OPN secreted by TM4SF4/GSK3β/β-catenin signaling activated the JAK2/STAT3 or FAK/STAT3 pathway, which also up-regulates OPN expression in an autocrine manner and consequently maintains the self-renewal and metastatic capacity of cancer cells." (PMID 29254164, 2017). "Therefore, the activation of critical signaling pathways related to tumorigenicity and cancer stemness, including JAK/STAT and SRC/FAK signaling pathway, were analyzed depending on TM4SF4 expression." (PMID 29254164, 2017). "Therefore, targeting TM4SF4 may reduce ICL expression by decreasing extracellular IGF1 and OPN levels, thereby improving the efficiency of cancer therapies." (PMID 41356204, 2026). "Tetraspanins, of which mRNA for TM4SF4, TM4SF20 and PLLP were increased >10-fold in SSA/Ps, regulate cell adhesion and proliferation by binding integrins and growth factor receptors, are increased in multiple types of cancer and regulate epithelial-to-mesenchymal transition." (PMID 24533081, 2014).